IGFBP2 (insulin like growth factor binding protein 2)
Diseases named in the same sentence as IGFBP2 in open-access papers (continued):
Sharing a sentence is not in itself a finding about the gene and the disease.
Hepatic steatosis (11 papers, 2018 to 2026). Steatosis is a term used to denote lipid accumulation within hepatocytes. "This implicates caution to differentiate whether the observed association of IGFBP2 with the degree of liver fat is an observation restricted to fatty liver disease." (PMID 32532003, 2020). "Reduced IGFBP2 expression in aggravated fatty liver was paralleled with promoter hypermethylation, reduced hepatic IGFBP2 secretion and IGFBP2 circulating in plasma." (PMID 32532003, 2020). "We further show that IGFBP2 blunts the stimulation of de novo lipogenesis by IGF1 in hepatocytes from healthy mice or mouse models with fatty liver disease." (PMID 32532003, 2020). "In patients with MASLD, IGFBP2 may exert a protective effect against hepatic steatosis progression but appears to play a negligible role in fibrogenesis." (PMID 40608848, 2025). "Subsequent studies have shown that IGFBP2 blunts the stimulation of de novo lipogenesis by IGF1 in hepatocytes from healthy mice or mouse models with fatty liver disease, suggesting that lower levels of IGFBP2 may exacerbate the development of MASLD." (PMID 40608848, 2025). "However, insulin signaling was not improved in vitro following FGFR4 KO, indicating that improved insulin signaling and Igfbp2 expression in vivo were likely a consequence of improved hepatic steatosis in these mice." (PMID 36586437, 2023). "Moreover, the level of insulin-like growth factor binding protein 2 (IGFBP2) is correlated with hepatic steatosis inversely, and both its genes and proteins were elevated in the RA group in the present study." (PMID 38049817, 2023). "Circulating IGFBP2 levels were associated with the histology-based hepatic steatosis score (r = −0.471, p < 0.001), but not with inflammation, ballooning, or fibrosis scores in the analyzed patients." (PMID 32532003, 2020). "This designates IGFBP2 as non-invasive biomarker for fatty liver disease progression and might further provide an additional variable for risk prediction for pathogenesis of fatty liver in diabetes subtype clusters." (PMID 32532003, 2020). "IGFBP2 may also influence hepatic steatosis through its interaction with IGF1." (PMID 40608848, 2025). "However, the relationship between circulating IGFBP2 and the severity of hepatic steatosis in patients with MASLD remains unknown." (PMID 40608848, 2025). "Consequently, reductions in IGFBP2 levels by lipids may aggravate the development of fatty liver disease." (PMID 32532003, 2020). "In conclusion, an RNA screening approach for regulatory network genes between mouse models with different degrees of fatty liver identified IGFBP2, a molecule integrated in the IGF system, as the central mediator between moderate and aggravated fatty liver." (PMID 32532003, 2020). "Our study demonstrates that the decreased serum level of IGFBP2 is an independent contributor to hepatic steatosis rather than hepatic fibrosis in patients with MASLD." (PMID 40608848, 2025). "Mechanistically, IGFBP2 inhibits IGF1 activation on DNL, and the reduction of IGFBP2 may, therefore, aggravate the development of fatty liver disease." (PMID 32532003, 2020). "This suggests that IGFBP2 may be involved in mitigating hepatic steatosis but does not appear to play a major role in liver fibrosis progression." (PMID 40608848, 2025).
epilepsy (10 papers, 2010 to 2026). A brain disorder characterized by episodes of abnormally increased neuronal discharge resulting in transient episodes of sensory or motor neurological dysfunction, or psychic dysfunction. "Therefore, while our results clearly implicate astrocytic Igfbp2 in the establishment of epilepsy, they also suggest that it contributes to modulating the properties of individual seizures." (PMID 41239819, 2026). "There may be a common link between P2Y1R and IGFBP2 in reactive astrocytes in several neurological diseases, such as epilepsy and stroke." (PMID 39117630, 2024). "In neurological disease models of epilepsy and stroke, reactive astrocytes upregulate P2Y1R and increase IGFBP2." (PMID 39117630, 2024). "In the present study, immunohistochemical data revealed that IGFBP2- and P2Y1R-positive astrocytes were similarly distributed in tissue affected by epilepsy (CA1) and stroke (dorsal striatum)." (PMID 39117630, 2024). "Furthermore, the finding that reactive astrocytes that express high levels of P2Y1R have upregulated IGFBP2 in epilepsy and stroke models suggests that P2Y1R-IGFBP2 signaling may be relevant to their pathogenesis, likely accompanied by neuronal hyperexcitability." (PMID 39117630, 2024).
leukemia (10 papers, 2010 to 2024). A malignant (clonal) hematologic disorder, involving hematopoietic stem cells and characterized by the presence of primitive or atypical myeloid or lymphoid cells in the bone marrow and the blood. "We studied the potential function of IGFBP2 in human leukemia cells by silencing its expression with lentivirus encoded small hairpin RNAs (shRNAs)." (PMID 24191913, 2013). "To determine the underlying mechanism by which IGFBP2 supports the growth of leukemia cells, we compared levels of apoptosis and cell cycle status of AML cells treated with shRNA3 or scrambled control shRNA." (PMID 24191913, 2013). "Indeed, consistent with the different expression of IGFBP2 in HSCs and leukemia cells, the signaling defects we observed in IGFBP2 deficient leukemia cells are more dramatic than in IGFBP2-null HSCs, and also are unique compared to defects observed in other cancer cells upon IGFBP2 deletion." (PMID 24191913, 2013). "Inhibition of endogenous IGFBP2 expression in human leukemia cells leads to increased apoptosis, decreased migration, and decreased activation of AKT and other signaling molecules." (PMID 38322990, 2024). "In contrast, with certain human leukaemias inhibition of IGFBP-2 resulted in a reduction in cell colony formation activity in a mouse model." (PMID 31903164, 2019). "The examination of leukemia infiltration into spleen and liver also revealed that IGFBP2-null AML cells less effectively induced leukemia than wild-type AML cells." (PMID 24191913, 2013). "Normal HSCs express little IGFBP2 per se, whereas both leukemia stem cells and differentiated leukemia cells have similar high expression of IGFBP2." (PMID 24191913, 2013). "Inhibition of IGFBP2 expression in human leukemia cell lines effectively inhibited growth of these cells." (PMID 24191913, 2013). "The deletion of IGFBP2 in donor AML cells significantly decreased leukemia development in transplanted mice." (PMID 24191913, 2013). "Our study suggests that the different effects of IGFBP2 on normal HSCs and leukemia cells contribute to this phenomenon." (PMID 24191913, 2013). "Concordantly, the expression of surface proteins (CX3CR1, CXCR4, EMB, ITGB4, LSP, VCAM1) important for leukemia infiltration was downregulated in IGFBP2-null bone marrow AML cells." (PMID 24191913, 2013). "Concordantly, here our study suggested that the AKT pathway in leukemia cells plays a critical role in the effects of IGFBP2, and we demonstrated that the PTEN inhibitor treatment rescues the colony forming activity of the IGFBP2 deficient leukemia cells." (PMID 24191913, 2013). "These novel data indicated that IGFBP2 supports leukemia development autonomously by both enhancing cell survival and promoting migration out of bone marrow and infiltration into peripheral organs and tissues." (PMID 24191913, 2013). "Together, our results suggest that IGFBP2 has cell-autonomous effects on leukemia cells and is critical for their survival and migration." (PMID 24191913, 2013). "To understand the potential functional role of IGFBP2 in leukemia development, we addressed several questions in the current study: 1) Is IGFBP2 expressed by leukemia cells?" (PMID 24191913, 2013). "Here we investigated the role of IGFBP2 in in human leukemia cells and in the retroviral AML1-ETO9a transplantation acute myeloid leukemia (AML) mouse model." (PMID 24191913, 2013). "Together with the migration enhancing effect of IGFBP2 in human leukemia cells, our results suggest that IGFBP2 enhances the mobilization of AML cells, thus accelerating AML development." (PMID 24191913, 2013). "Inhibition of expression of endogenous IGFBP2 in human leukemia cells led to elevated apoptosis and decreased migration and, consistently, to decreased activation of AKT and other signaling molecules." (PMID 24191913, 2013). "For instance, the expression level of IGFBP2 is high in leukemia." (PMID 38322990, 2024).
leukemia (continued). "In this work, we evaluated the use of human IGFBP2, B2M or Hsp90 as soluble markers of leukemia." (PMID 26068922, 2015). "Importantly, similar to the human leukemia cells, the deletion of IGFBP2 induced increased apoptosis of mouse bone marrow AML cells." (PMID 24191913, 2013). "While a major question in IGFBP biology is whether the effect of IGFBP2 is environmental or cell-autonomous, our studies on HSCs and leukemia indicated that the answers are cell-type-dependent." (PMID 24191913, 2013). "We next examined whether ERK and AKT signaling are involved in the effects of IGFBP2 on these leukemia cells." (PMID 24191913, 2013). "While IGFBP2 is expressed at high levels by M3 t(15:17) APL cells that produce a fusion protein promyelocytic leukemia-retinoic acid receptor α (PML-RARA), the physiologic PML-RARA expression from the mouse pml locus rarely causes leukemia development." (PMID 24191913, 2013). "IGFBP-2 was identified as the major regulatory carrier in childhood leukemia and exhibited an inverse correlation with IGF-1 levels, suggesting that activation of IGF-1R signaling may confer ALL cells a survival advantage and influence induction of apoptosis." (PMID 20863384, 2010). "This analysis also pointed to the higher expression of several other genes normally deregulated in a wide spectrum of leukaemias, including genes that act as transcriptional regulators (PRDM16 and NFIX) and a gene that influences proliferative advantage and survival (IGFBP2)." (PMID 32103106, 2020). "The inclusion of extrinsic recombinant IGFBP2 in the culture medium did not rescue the defects in leukemia cells treated with shRNA targeting IGFBP2." (PMID 24191913, 2013).
Alzheimer disease (8 papers, 2018 to 2026). A progressive, neurodegenerative disease characterized by loss of function and death of nerve cells in several areas of the brain leading to loss of cognitive function such as memory and language. "IGFBP-2 has also been shown to be associated with early stages of Alzheimer’s disease progression." (PMID 37982669, 2024). "There is also a significant difference in CSF IGFBP2 levels in Alzheimer's disease, which shows cognitive dysfunction." (PMID 37786962, 2024). "Analysis of publicly available databases of Alzheimer’s disease models (GSE183050, GSE129797, GSE138695) did not reveal changes in Igfbp2/IGFBP2." (PMID 39117630, 2024).
bladder cancer (8 papers, 2017 to 2025). "To investigate whether the loss of IGFBP-2 in mesenchymal-like bladder cancer cells potentially resulted from epigenetic regulation, we initially treated the mesenchymal T24 and TCCSUP cells with a demethylating agent, AZA." (PMID 31903164, 2019). "Based on the reversible nature of epigenetic modifications, compared with genetic mutations, these findings suggest IGFBP-2 is switched off in advanced bladder cancer which eliminates the inhibitory effects of this protein on cell proliferation, invasion and colony formation in cancer development." (PMID 31903164, 2019). "There is also little information about the relative abundance of IGFBP-2 in luminal versus basal bladder cancers." (PMID 31903164, 2019). "In this study we determined the role that IGFBP-2 played on proliferation, invasion, EMT, colony formation and chemosensitivity in a selection of bladder cancer cell lines and investigated how the abundance of IGFBP-2 was regulated." (PMID 31903164, 2019). "In contrast to the sparce data on a possible role for IGFBP-2 in chemosensitivity of bladder cancer, there are convincing data indicating a role for ERCC2 mutations." (PMID 31903164, 2019). "In contrast, mesenchymal bladder cancer cells appear to have negligible levels of IGFBP-2 that correlate with a more aggressive cell type." (PMID 31903164, 2019). "Whilst these data contradict our results and suggest that IGFBP-2 plays a role in inhibiting malignant transformation in bladder cancer, the methodology used to assess the role of IGFBP-2 was very different." (PMID 31903164, 2019). "Collectively these data suggest that IGFBP-2 acts as a tumour suppressor and marker of chemosensitivity in epithelial bladder cancer cells and that IGFBP-2 is epigenetically silenced by methylation to promote bladder cancer progression." (PMID 31903164, 2019). "The same group also determined that IGFBP-2 mRNA expression levels and the relative expression ratio of IGFBP-2 to IGFBP-3 mRNAs in 97 bladder cancer specimens significantly correlated with pathological stage, lymph node metastasis and vascular invasion." (PMID 31903164, 2019). "In this study we determined the role that IGFBP-2 played on the phenotype and chemosensitivity of a selection of bladder cancer cell lines and investigated how the abundance of IGFBP-2 was regulated." (PMID 31903164, 2019). "Inhibiting IGFBP2 improves the sensitivity of bladder cancer cells to cisplatin by elevating the expression of maspin." (PMID 28903396, 2017). "There are limited reports on the role of IGFBP-2 in bladder cancer progression." (PMID 31903164, 2019). "We next investigated if altered methylation may be the mechanism by which IGFBP-2 levels were being regulated in bladder cancer cells." (PMID 31903164, 2019). "However, in bladder cancer over-expression of IGFBP-2 enhanced the invasive potential of KoTCC cells." (PMID 31903164, 2019). "Our work also provides preliminary data suggesting that the presence of IGFBP-2 in bladder cancer cells may enable them to be more responsive to chemotherapy, but this requires further investigation." (PMID 31903164, 2019). "In summary, these data suggest that IGFBP-2 may act as a tumour suppressor in bladder cancer cells as it inhibits cell growth, invasion, colony formation and reduces markers of EMT." (PMID 31903164, 2019). "Furthermore, methylation may be one mechanism that bladder cancers use to reduce levels of IGFBP-2 to promote carcinogenesis." (PMID 31903164, 2019). "Moreover, KD of DEPDC1B significantly inhibited cell proliferation of bladder cancer, and promoted cell apoptosis through the regulation of Caspase-3, clAP-2, IGF-I, IGFBP-2, IGF-1sR, Livin, TNF-β, TRAILR-3, and TRAILR-4." (PMID 33203836, 2020). "As it has been reported that IGFBP-2 can act in either an IGF-dependent or -independent or both manners, NBI-31772, as an inhibitor of IGF/IGFBP-2 interactions, was used to study how it works in bladder cancer." (PMID 31903164, 2019).
bladder cancer (continued). "Our data suggest that IGFBP-2 acts to inhibit cell proliferation, invasion, colony formation and EMT in bladder cancer and its presence may play a role in determining chemosensitivity." (PMID 31903164, 2019).
chronic pancreatitis (8 papers, 2016 to 2025). A chronic inflammatory process causing damage and fibrosis of the pancreatic parenchyma. "A second confirmatory phase on an independent cohort of 131 PDAC patients, 30 chronic pancreatitis patients, and 131 healthy subjects confirmed the PDAC association for MMP7, CCN2, IGFBP2, TSP2, sICAM1, TIMP1, and PLG." (PMID 29941541, 2018). "Significant AUC values of IGFBP2 were observed with IPMNs, endocrine neoplasms and chronic pancreatitis against healthy controls." (PMID 27579675, 2016). "IGFBP2 was more accurate than the other in discriminating between chronic pancreatitis and PDAC." (PMID 39221034, 2024). "However, due to the limited number of chronic pancreatitis samples, further study is necessary to establish whether IGFBP2 is available as a marker to discriminate IDACP from chronic pancreatitis." (PMID 27579675, 2016). "Our purpose was to investigate plasma IGFBP2 levels in PDAC patients, chronic pancreatitis patients, and matched healthy controls in a Chinese cohort." (PMID 39221034, 2024). "In fact, both IGF-1 and IGFBP-2 (insulin-like growth factor binding protein-2) were also suggested as possible biomarkers which could help to differentiate PDAC from healthy controls and patients with other diseases, such as chronic pancreatitis." (PMID 40299428, 2025).